PTH (parathyroid hormone)
Diseases named in the same sentence as PTH in open-access papers (continued):
Sharing a sentence is not in itself a finding about the gene and the disease.
Hypertension (continued). "Later on, a similar increase in serum PTH was demonstrated in association with increased urinary calcium excretion, lower serum calcium concentrations, and comparable vitamin D levels in patients with primary aldosteronism in comparison to patients with essential hypertension." (PMID 29056965, 2017). "Simulations of hypertension, induced by various stimuli like increased renin or aldosterone secretion, demonstrated significant effects on parathyroid hormone (PTH), calcitriol, renal Ca2+/Mg2+ handling, and bone resorption." (PMID 41637481, 2026). "Of the four patients with persistently elevated PTH, three had normalised calcium but all four had residual hypertension." (PMID 40608198, 2025). "Lower 25(OH)D levels were associated with older age (p < 0.001), longer duration of hypertension (p = 0.019), higher fasting plasma glucose (p = 0.037), and insulin (p = 0.044), Homeostatic Model Assessment (HOMA) index (p = 0.044), and PTH (p < 0.001)." (PMID 39940336, 2025). "Lower 25(OH)D levels were associated with significantly older age, longer duration of hypertension, greater fasting plasma glucose and insulin, HOMA index, and plasma PTH." (PMID 39940336, 2025). "Logistic multifactor regression analysis of the basic data of patients in the HD group revealed that age, hypertension, PTH, serum creatinine, and PVD were factors that influenced the survival rate of patients (p < .05)." (PMID 38482569, 2024). "Participants with high PTH levels are more likely to have lower family income and lower education levels, a higher incidence rate of hypertension, and lower rates of alcohol consumption and smoking." (PMID 38982174, 2024). "When comparing high versus low PTH level, the pooled OR for hypertension was 1.24 (95% CI: 1.16–1.33, I2 = 39.6%, Pheterogeneity=0.115)." (PMID 38172768, 2024). "Our study provided the first systematic review and meta-analysis of cohort and cross-sectional studies of the dose-response relationship between PTH and hypertension and T2D." (PMID 38172768, 2024). "First, this is the first meta-analysis to evaluate the dose-response relationship between PTH and hypertension and T2D." (PMID 38172768, 2024). "Lastly, the involvement of PTH in the Renin–Angiotensin–Aldosterone axis highlights the importance of opting for the appropriate pharmacological agent should hypertension develop." (PMID 38785509, 2024). "Clinical studies have reported a clear association between inadequate calcium consumption and elevated levels of parathyroid hormone (PTH) levels, which can lead to hypertension in the long term." (PMID 37895858, 2023). "In some studies, hypertension is related to low BMD as a consequence of increased serum parathyroid hormone (PTH) levels or urinary calcium excretion, but the results are conflicting." (PMID 38357185, 2023). "Significant differences were observed between both groups in donor age, donor hypertension, intact PTH level before PKT, and preoperative donor eGFR." (PMID 37351681, 2023). "The mechanistic actions of PTH to hypertension include the increase in renin secretion as well as its direct effects on arteries and myocytes to promote arterial stiffness and left ventricular hypertrophy." (PMID 36364791, 2022). "PTH has been shown to have a prosclerotic effect on blood vessels which contributes to atherosclerosis of blood vessels and the development of hypertension." (PMID 36389124, 2022). "It is suggested that high blood pressure increases calcium excretion, elevates parathyroid hormone level and thus increases bone resorption." (PMID 35334861, 2022). "In a cross-sectional study of 192 hypertensive patients, patients with primary aldosteronism had higher plasma PTH concentrations than patients with essential hypertension." (PMID 36389124, 2022). "A 54-year-old female with recently diagnosed Graves’ disease presented hyperkalemia, hypertension, hypercalciuria, elevated levels of parathyroid hormone (PTH) and normal renal function." (PMID 34022862, 2021).
Hypertension (continued). "There have been studies in dialysis patients showed increasing VC severity with age, regardless of factors such as dialysis vintage, dyslipidemia, PTH level and hypertension." (PMID 33815281, 2021). "There was also a significant interaction between PTH and race/ethnicity on hypertension (P for interaction = 0.008)." (PMID 34531372, 2021). "There was a statistically significant in serum phosphorus (p value = 0.03), serum PTH (p value = 0.002), and hypertension (p value = 0.03)." (PMID 34539794, 2021). "It is generally thought that high blood pressure increases the excretion of calcium, resulting in an increase in parathyroid hormone level and subsequent bone resorption." (PMID 34065445, 2021). "Regression analysis assessed the impact of hypertension, DM, age, baseline serum calcium, creatinine, eGFR, and PTH levels on eGFR changes." (PMID 32118376, 2020). "A study with 1784 individuals with mild renal dysfunction or normal eGFR followed for seven years revealed that PTH levels were able to predict hypertension in men, even after adjustments for age, smoking, and body mass index." (PMID 32192220, 2020). "Bariatric patients with renal failure, hypertension, and anemia would likely benefit from earlier follow-up with parathyroid axis monitoring (i.e., outpatient monitoring of calcium, vitamin D, and PTH levels)." (PMID 33110721, 2020). "Fourthly, PTH can also increase plasma renin activity (PRA) and thereby increase blood pressure, while hypertension is associated with vascular calcification and aging." (PMID 32973674, 2020). "It is generally agreed that high blood pressure increases the excretion of calcium, thus elevating parathyroid hormone level and bone resorption." (PMID 33029101, 2020). "Chronic PTH elevation was correlated with coronary microvascular dysfunction, cardiac hypertrophy, impaired glucose and lipid mechanisms, arterial hypertension, endothelial dysfunction, and subclinical aortic valve calcification." (PMID 31068134, 2019). "Individuals with primary aldosteronism have higher PTH levels when compared to matched individuals with essential hypertension." (PMID 28808443, 2017). "Spline curves were used to estimate thresholds for falling, fractures, hypertension, cardiovascular disease, blood pressure, PTH, grip strength, physical performance, functional limitations, BMI, and mortality." (PMID 27544533, 2016). "His serum PTH level was almost undetectable; he had mild alkalosis, renal failure with eGFR of 42 ml/min, anemia, hypertension and abnormal ECG with shortened QT interval and ST elevation in V1-V4." (PMID 27335601, 2016). "The estimated thresholds differed by sex and age groups, and varied from 46 (PTH) to 68 nmol/L (hypertension)." (PMID 27544533, 2016). "Mais des effets délétères liés à l’élévation de la PTH ont été décrits, notamment l'hypertension artérielle, l'ostéoporose et l’élévation de la mortalité globale." (PMID 25815104, 2014). "This group included all diabetics, all but 2 with CAC, the highest percentage of patients with hypertension and low PTH level (<100 pg/mL)." (PMID 23317172, 2013). "Prospective population studies are needed to evaluate the role of vitamin D and PTH in the incidence of hypertension." (PMID 22937036, 2012). "Some studies have shown that patients with essential hypertension have a higher serum concentration of PTH than normotensive individuals." (PMID 21403888, 2011). "A recently published link between PTH and MS in older men was explained by insulin resistance, high blood pressure, hyperglycemia and low HDL-cholesterol." (PMID 21306649, 2011). "The recently published link between PTH and MS in older men, was explained by insulin resistance, high blood pressure, hyperglycemia and low HDL-cholesterol." (PMID 19187564, 2009).
Hypertension (continued). "The relationship was more evident among patients with hypertension, impaired renal function, or low magnesium levels, indicating that vascular strain, renal stress, and mineral imbalance may heighten PTH activity." (PMID 42224245, 2026). "The literature describes a correlation between PTH levels and aldosterone levels, where elevated PTH concentrations may induce increased aldosterone secretion, hypertension, and cardiovascular complications." (PMID 40666157, 2025). "In general, this dose-response meta-analysis shows a positive correlation between PTH levels and the risk of hypertension, but there is no statistical significance between PTH and T2D." (PMID 38172768, 2024). "Hypovitaminosis D may elevate the levels of intact parathyroid hormone, leading to arterial hypertension, unfavorable vascular remodeling, and calcification of the vascular wall." (PMID 38892508, 2024). "In contrast, age, hypertension, parathyroid hormone (PTH), serum creatinine, and peripheral vascular diseases (PVD) influenced the survival rate of patients in the HD group (p < .05), and age and weight influenced the survival rate of patients in the PD group (p < .05)." (PMID 38482569, 2024). "Third, there was publication bias in the meta-analysis to assess the risk of PTH and hypertension, however, the results did not change substantially by the trim-and-fill methods." (PMID 38172768, 2024). "In PubMed, Web of Science and Embase, we identified a total of ten articles (13 independent studies), among which eight (five cohort, three cross-section) were about the studies on PTH and hypertension, and five (two cohort, three cross-section) on PTH and T2D." (PMID 38172768, 2024). "Despite an increase in parathyroid hormone (PTH) has been reported to be associated with a higher risk of hypertension and type 2 diabetes (T2D), the comprehensive evaluation of the dose-response relationship between PTH and hypertension and T2D remains ambiguous." (PMID 38172768, 2024). "In addition to age, hypertension, and serum creatinine, the factors influencing the survival rate of patients on HD included PTH and PVD." (PMID 38482569, 2024). "It hinted that the detection method of PTH may impact the relationship between PTH and hypertension." (PMID 38172768, 2024). "Thus, PTH activity increases dramatically, which is known to influence the mechanism of hypertension by raising intracellular calcium levels." (PMID 37233176, 2023). "One explanation is that the link between the two may be due to hypertension, as lowering blood pressure can increase plasma calcium by reducing renal calcium and magnesium excretion, ultimately resulting in decreased PTH levels." (PMID 37968749, 2023). "It is also thought that PTH might block the interchange of sodium and hydrogen, which adds to the impact of spontaneous hypertension." (PMID 37233176, 2023). "In other aspects, higher PTH levels exacerbate arterial stiffness, endothelial dysfunction, and arterial hypertension, all of which could contribute to diastolic cardiac dysfunction." (PMID 36824357, 2023). "Dietary vitamin D supplementation for patients with hypertension/inflammatory disease may be used to achieve PTH inhibition; hence, the blood-pressure-lowering effect of vitamin D may also be partially regulated by PTH." (PMID 35814306, 2022). "Similarly, increased PTH plasma levels are related to hypertension, left ventricular hypertroph and increased cardiovascular events." (PMID 35887917, 2022). "Besides, the CKD 3–5 group also showed significantly higher results of age, BMI, PTH, β2-M, history of hypertension, and CVD compared to the CKD 1–2 group (all p < 0.05)." (PMID 34867144, 2021). "Theoretically, hypertension may be related to low bone mass due to changes in serum intact parathyroid hormone concentration and urinary calcium excretion; however, the results are controversial." (PMID 34065445, 2021).
Hypertension (continued). "Although the 2017 KDIGO guidelines of CKD-MBD have recommended monitoring serum concentrations of calcium, phosphorus, and intact parathyroid hormone beginning in stage 3 CKD, our subsidiary analyses indicated that the risk prediction of these markers hinged upon sex and hypertension status." (PMID 33725210, 2021). "Compared to functionally independent patients, those reporting functional dependence had a higher mean age, lower concentrations of parathyroid hormone (PTH) and serum creatinine, higher proportion of hemodialysis by catheter and higher prevalence of comorbidities (except hypertension)." (PMID 32680521, 2020). "Despite the evidence linking PTH with hypertension, the unanswered question is whether this relationship is causal." (PMID 32192220, 2020). "Univariate logistic regression analysis indicated that hypertension (odds ratio [OR[: 0.032; 95% confidence interval [CI]: 0.001–0.475; P = 0.012), and parathyroid hormone level (OR: 1.006; 95% CI: 1.004–1.009; P = 0.044) were associated with the > 10% BMD increase." (PMID 32928178, 2020). "There is some evidence of a correlation between serum levels of PTH and hypertension." (PMID 32192220, 2020). "A positive correlation between increased PTH level and hypertension was observed." (PMID 31068134, 2019). "In particular, in PHPT patients with and without hypertension PTH levels are negatively associated with retinal vessel diameter." (PMID 30410012, 2018). "Furthermore, hypertension (OR: 3.23, 95% CI: 1.61–6.48, P = 0.001), intact PTH (OR: 1.02, 95% CI: 1.01–1.02, P = 0.027), and IVCCI < 50% (OR: 9.22, 95% CI: 1.91–44.49, P = 0.006) were independent predictors of LVDD." (PMID 30325973, 2018). "In conclusion, we found macro-vascular impairment in PHPT and that micro-vascular impairment is negatively associated with PTH, regardless of hypertension in PHPT." (PMID 30410012, 2018). "Some researchers hypothesize excess PTH secretion to be involved in the development of hypertension, a theory supported by data indicating a positive correlation between blood pressure and serum concentrations of PTH." (PMID 28272298, 2017). "Low calcium levels may lead to hypertension by stimulating either the parathyroid hormone (PTH) or renin release, resulting in vasoconstriction due to increased intracellular calcium in vascular smooth muscle." (PMID 28709403, 2017). "Consequently, in addition to low Vit-D concentrations in Sarc+ participants, we discovered the specific association between PTH and Sarc+ LVH+ participants independently of hypertension and of calcium or phosphate concentration." (PMID 28112206, 2017). "It is possible that lower 25(OH)D and higher serum PTH levels could synergistically or independently play a role in the pathogenesis of developing hypertension and future CVD." (PMID 28241878, 2017). "Moreover, OPG was directly correlated with SBP (p < 0.0001), hypertension duration (p = 0.0018), PTH (p < 0.0001), phosphate (p < 0.0001), CRP (p < 0.0001), and macrovascular events (p < 0.0001)." (PMID 28683789, 2017). "Recurrence was preceded by rising serum calcium and PTH concentrations and recurrent hypertension." (PMID 24823466, 2014). "The prognostic significance of preoperative PTH levels for the reversibility of hypertension and cardiovascular complications has to be further evaluated in prospective studies and there may be reasons to reevaluate the guidelines." (PMID 24026893, 2013). "In conclusion, our study suggests that serum vitamin D and PTH levels are not independently associated with blood pressure or risk of hypertension in a Chinese population." (PMID 22937036, 2012). "Serum vitamin D and PTH levels are not independently associated with blood pressure or risk of hypertension in a Chinese population." (PMID 22937036, 2012).
Hypertension (continued). "In the NHANES 2003-2006, both 25(OH)D and PTH were associated with BP and the prevalence of hypertension in participants aged ≥ 20 years not taking antihypertensive medicine, but the association of 25(OH)D with BP attenuated when adjusted for PTH." (PMID 22433818, 2012). "The main findings of our cross-sectional study are that serum 25(OH)D and PTH levels are not independently associated with blood pressure level or risk of hypertension in a Chinese population." (PMID 22937036, 2012). "Associations (ORs with 95%CI) of serum 25(OH)D and natural log of PTH levels with the risk of hypertension in participants without antihypertensive treatment." (PMID 22937036, 2012). "The hypothesis that PTH may be involved in the pathogenesis of hypertension is also supported by a prospective population based cohort study." (PMID 19187564, 2009). "Notably, a cohort study found that elevated PTH levels, overall, were not independently associated with the risk of hypertension, but the relationship was observed among blacks not white." (PMID 38172768, 2024). "Moreover, we found that the association between PTH and risk of hypertension was not statistically significant in Korean and Netherlands." (PMID 38172768, 2024). "Also, Elevated PTH levels may promote hypertension, due to its correlation with aldosterone levels PTH could directly stimulate aldosterone synthesis." (PMID 36773188, 2023). "The authors suggested a possible role for PTH in increasing blood pressure by acting directly on vessels or through the renin–angiotensin–aldosterone system, and concluded that surgery with normalization of PTH levels might be beneficial in controlling hypertension." (PMID 32803112, 2020). "Furthermore, hypertension, intact PTH, and IVCCI < 50% were independent predictors of LVDD." (PMID 30325973, 2018). "In addition, age (OR: 1.05, 95% CI: 1.01–1.08, P = 0.005), hypertension (OR: 4.57, 95% CI: 1.83–11.41, P = 0.001), intact PTH (OR: 1.01, 95% CI: 1.01–1.02, P = 0.001), and IVCCI < 50% (OR: 4.10, 95% CI: 1.39–12.08, P = 0.011) were independent predictors of LVH." (PMID 30325973, 2018). "In addition, hypertension, intact PTH, and IVCCI < 50% were independent predictors of LVH." (PMID 30325973, 2018). "Second, PTH has been linked to hypertension in previous studies, independent of vitamin D levels." (PMID 28358827, 2017). "Underlying hypertension and CKD also strengthen the linkage between diastolic dysfunction and CIN through the effects of uremic toxin, pressure overload, RAAS activation, and markedly elevated expression of humoral mediators such as catecholamines, endothelin, and parathyroid hormone." (PMID 23849485, 2013). "The lack of association between serum PTH levels and blood pressure, or risk of hypertension might be attributed to the relatively low levels of serum PTH in our study [median concentration 2.83 pmol/l (26.9 ng/l)]." (PMID 22937036, 2012). "Log 25(OH)D levels were significantly and negatively correlated with age, duration of hypertension, glucose, HOMA index, and serum PTH." (PMID 39940336, 2025). "For the total hip, the most influential predictors of bone loss were baseline 25-OH vitamin D (mean |SHAP| = 0.79), comorbidities (0.67), hypertension (0.64), and NSAID use (0.58), followed by baseline PTH (0.45)." (PMID 41404357, 2025). "The physiology of markers of mineral metabolism, such as PTH and calcium, is intricately intertwined and may vary by race, so within-subject biological variations are very significant, and thus impedes clinical application of PTH as a predictor of hypertension." (PMID 38172768, 2024). "Moreover, the level of PTH is closely related to serum calcium concentrations, and multiple epidemiological studies have shown that low levels of dairy calcium intake may be related to the high prevalence of hypertension." (PMID 38172768, 2024).